GCG (glucagon)
Diseases named in the same sentence as GCG in open-access papers (continued):
Sharing a sentence is not in itself a finding about the gene and the disease.
Obesity (continued). "Semaglutide, a glucagon-likepeptide-1 (GLP-1) receptor agonist,constitutes an effective and widely used treatment for type 2 diabetesand obesity." (PMID 40305415, 2025). "Children and adolescents with obesity and insulin resistance have increased levels of fasting plasma glucagon and GLP-1, increased glucagon, and diminished GLP-1 responses during the OGTT, corresponding with reduced insulin sensitivity and β-cell function." (PMID 40649920, 2025). "There is an impressive number of obesity management medications under investigation, such as GLP1/glucagon dual agonists, GIP/GLP1 dual agonists, GIP/GLP1/glucagon tri-agonists, leptin sensitizers, etc.." (PMID 39274320, 2024). "As a result, in case of obesity, insulin and GLP-1RA inhibits physiological glucagon functions while GLP-1RA stimulates insulin secretion disbalancing the equilibration of fasting/postprandial state." (PMID 38579770, 2024). "In sum, these data suggest that, in individuals with obesity and insulin resistance, GLP-1, GIP and glucagon are likely to increase AT’s metabolic efficiency despite this effect being attained via different mechanisms and potentially acting in synergy." (PMID 37233628, 2023). "The therapeutic spectrum of T2D and obesity therapy has recently been enriched by hybrid peptides acting as triple GLP-1R/GIPR/GCGR agonists that target both incretin and glucagon signalling to synergistically elicit favourable metabolic effects." (PMID 37378828, 2023). "For this, we conducted an in vitro study in which the VAT of individuals with obesity with different glycemic statuses and normal-weight euglycemic control was exposed to GLP-1, GIP and glucagon in different concentrations." (PMID 37233628, 2023). "Increased fasting levels of glucagon can be found in T2DM patients and in subjects with obesity and normal glucose tolerance." (PMID 36133310, 2022). "Adolescents with obesity and NGT had 30% higher fasting glucagon than controls, glucagon levels increased with a decline in glucose tolerance." (PMID 36686477, 2022). "Still, higher fasting glucagon and late glucagon-suppression during OGTT are consistent findings in prediabetes, T2D, obesity and the metabolic syndrome." (PMID 36686477, 2022). "In preclinical models, it had been shown before that dual GLP-1/GCG as well as dual GLP-1/GIP agonists improve metabolic parameters and are capable of fighting obesity." (PMID 36552107, 2022). "A standardized multivariate regression model was constructed based on the glucagon predictors BMI-SDS, average liver fat, fasting insulin, glucose at 120 min, SPISE and ALT in overweight and patients with overweight/obesity." (PMID 36133310, 2022). "In adolescents with obesity (both NGT and IGT), glucagon levels showed an increasing trend in the first five minutes without declining below baseline in the first 30 minutes." (PMID 36686477, 2022). "The combination of lipolytic and thermogenic actions of glucagon with the anorectic and insulinotropic actions of GLP-1 is crucial for the targeted management of obesity." (PMID 34577569, 2021). "Under a pathological condition such as obesity-induced oxidative stress, fatty acid (palmitate) would have relatively high affinity for FABP4, which would facilitate glucagon secretion from α-cells." (PMID 34174950, 2021). "On the other hand, glucagon enhances energy consumption and acts as food intake regulator, making its analogues also interesting for glucose regulation in T2DM and obesity." (PMID 34195230, 2021). "The related genes of obesity (ADIPOQ, GCG, PCSK1N, TFAP2A, and PYY) were also found to play significant roles in the occurrence of some types of cancer (BRCA, COAD, and UCEC)." (PMID 33299884, 2020). "In this short review, we will summarize the latest evidence in this regard, as well as the current therapeutic glucagon- and GLP-1-based approaches to treating obesity." (PMID 31337027, 2019).
Obesity (continued). "The first developed molecule aimed to simultaneously activate glucagon and GLP-1 receptors for the treatment of obesity and glucose intolerance, improving body weight and glycemic control in a similar manner to exendin-4, a GLP-1 analogue." (PMID 31337027, 2019). "Recently we have published that anti-obesity effect of menthol, a TRPM8 agonist is mediated through glucagon dependent mechanisms particularly in adipose tissues." (PMID 31027377, 2019). "In states of obesity/DT2, when insulin production is upregulated, glucagon secretion should be downregulated, however, the opposite situation is observed, another aspect of the “enigma” concerning the mechanisms controlling glucagon secretion." (PMID 30293998, 2018). "The prevalence of incidental gastric NETs in obesity surgery candidates was found to be high and the occurrence of a pNET co-secreting GLP-1 and glucagon in a patient previously submitted for gastric bypass surgery was also reported." (PMID 30150555, 2018). "Central GCG, therefore, exerted its acute anorectic effects through PKA/AMPK/CaMKKβ-dependent pathways in the ARC and CaMKKβ mediated its obesity-induced hypothalamic resistance." (PMID 28223965, 2017). "Several studies have also reported no abnormalities in fasting glucagon or postprandial glucagon areas under the curve (AUC) in individuals with obesity versus their lean counterparts." (PMID 41575482, 2026). "More recently, dual and triple incretin agonists, targeting combinations of GLP-1, glucose-dependent insulinotropic polypeptide (GIP), and glucagon (GCG), have achieved even greater weight reductions in clinical trials, raising the prospect of unprecedented efficacy in medical obesity treatment." (PMID 41465555, 2025). "GLP-1R neurons in the PVH receive projections from the NTS, activation of glucagon (Gcg) neurons in the NTS inhibits feeding behaviors, while deletion of PVHGLP-1R neurons increases food intake and decreases locomotor activities, leading to obesity." (PMID 39974186, 2025). "The development of triple agonists for obesity has built upon successes of several dual combinations of entero-pancreatic hormone receptor agonists, in particular, GLP-1/GIP dual agonists and GLP-1/GCG dual agonists." (PMID 40741227, 2025). "By increasing insulin secretion, inhibiting glucagon, and decreasing the consumption of calories through decreased gastrointestinal motility and central anorectic processes, GLP-1 receptor agonists like semaglutide have anti-obesity benefits." (PMID 40649920, 2025). "Trials investigating newer potential anti-obesity medications, including co-agonists and tri-agonists that target peptides such as GLP-1, glucose-dependent insulinotropic polypeptide (GIP), amylin, and glucagon are underway." (PMID 41153573, 2025). "Supporting this model, a 2020 study demonstrated impaired glucagon-mediated amino acid turnover in the liver of individuals with obesity and NAFLD compared to lean, non-steatotic controls." (PMID 41149695, 2025). "Furthermore, children and adolescents with obesity and insulin resistance had elevated glucagon levels and diminished GLP-1 responses during the OGTT, in comparison to their counterparts with obesity and insulin sensitivity or those with normal weight." (PMID 40649920, 2025). "This could indicate that patients with obesity and MASLD are resistant to the effects of glucagon on amino acid uptake and catabolism." (PMID 38579751, 2024). "Identification of the specific molecular characteristics responsible for the beneficial effects of glucagon on hepatic lipid turnover may be crucial in developing improved glucagon co-agonists for the treatment of MASLD and obesity." (PMID 38705923, 2024). "It is worth noting, however, that an increase in energy expenditure was not reported following chronic administration of glucagon (72 h) in individuals with overweight/obesity." (PMID 38579751, 2024).
Obesity (continued). "This is in line with increased glucagon gene expression, suggesting that SGLT1/2 may play different roles in obesity, warranting further exploration." (PMID 38644407, 2024). "Children and adolescents with obesity and normal insulin sensitivity do not exhibit similar alterations in glucagon and incretin secretion, highlighting potential for targeted interventions." (PMID 38087928, 2024). "In summary, fasting glucagon levels were lower in the control subgroup without obesity compared to the other three subgroups." (PMID 38276866, 2024). "Conversely, the reversal of obesity and insulin resistance by gastric bypass surgery is preceded by attenuated HPA as well as glucagon responses to glucose lowering, which could contribute to the antidiabetic effects of this intervention." (PMID 37708362, 2024). "In the control subgroup without obesity, who were expected to be the most metabolically healthy of the four subgroups, we observed the lowest fasting concentrations of total amino acids, glucagon, insulin, and hepatic fat content (as measured by CAP)." (PMID 38276866, 2024). "Furthermore, due to insulin resistance and elevated blood glucagon levels, there is an increase in adipose tissue lipolysis and the release of free fatty acids (FFA) into circulation in patients with T2DM and obesity." (PMID 36836874, 2023). "Differences were obtained between patients without obesity and stable plaques and without obesity and unstable plaques for glucagon (p = 0.040), insulin (p = 0.011)." (PMID 36013196, 2022). "In summary, Gpr151 loss impairs hepatic glucogenesis regardless of the presence of glucagon, which likely explains its effects on whole-body glucose metabolism in diet-induced obesity." (PMID 36456565, 2022). "Jejunal EECs isolated from patients with T2DM also demonstrate downregulation in genes involved in EEC differentiation (including PAX4 and FOXA2) and in the GCG gene itself, indicating that jejunal GLP-1+ cell differentiation and number are negatively affected by both obesity and T2DM." (PMID 35503251, 2022). "The importance of the liver in mediating the anti-obesity action of glucagon administration is exemplified by findings in liver-specific knockout models, where the absence of the GCGR ablates the ability of glucagon to induce weight loss." (PMID 35547006, 2022). "In preclinical studies, the glucagon-GCGR system affects key metabolically relevant organs (including the liver and white and brown adipose tissue) to boost whole-body thermogenic capacity and protect from obesity." (PMID 35547006, 2022). "The obesity panel revealed BDNF was increased while both leptin and glucagon were reduced." (PMID 35574470, 2022). "The process of autophagy has been shown to be impaired in obesity and NAFLD, and hepatic resistance to glucagon in subjects with NAFLD may therefore partly explain the impaired autophagy." (PMID 33333850, 2020). "In addition, five related genes of obesity (ADIPOQ, GCG, PCSK1N, TFAP2A, and PYY) were distributed in the top 25 over/underexpressed genes of cancer tissues." (PMID 33299884, 2020). "The non-glycemic effects of glucagon render this molecule an interesting target for the treatment of obesity." (PMID 31671603, 2019). "Supporting these data, other glucagon/GLP-1 receptor co-agonists have been reported to lower plasma concentrations of TG and cholesterol, decrease hepatic fat content, and reduce adipose mass in rodent models of T2D and obesity." (PMID 31068828, 2019). "Thus, glucagon decreases food intake acutely via PKA/CaMKKβ/AMPK dependent pathways in the ARC, and CaMKKβ mediates its obesity-induced hypothalamic resistance." (PMID 26909312, 2015). "However, the administration of the dual agonists stimulating both glucagon and GLP-1 receptors achieved improvement of diet-induced obesity and glucose intolerance." (PMID 22899902, 2012).
Obesity (continued). "Mammalian type 1 diabetes is similarly characterized by high blood glucose, the absence of obesity, reduced insulin production, and inadequate suppression of glucagon secretion." (PMID 22761585, 2012). "There is currently no consensus regarding the postprandial glucagon response in obesity." (PMID 41575482, 2026). "Additionally, we did not measure obesity-related markers such as insulin, C-peptide, glucagon, leptin, or cortisol." (PMID 41323348, 2025). "The third generation of nutrient-stimulated hormone-based (NuSH) anti-obesity medications (AOM), which includes co- and tri-agonists that combine peptides such as GLP-1, glucose-dependent insulinotropic polypeptide (GIP), amylin, and glucagon, is poised to commence clinical trials in adolescents." (PMID 40014613, 2025). "However, Myf5 promoter-driven deletion of GCGR in BAT did not affect diet-induced obesity or glucagon-induced energy expenditure." (PMID 40892365, 2025). "However, the increase in glucagon levels after glucose loading in the control group (that consisted of patients with obesity without T2D) is not so obvious." (PMID 39598143, 2024). "This study explores the scope of construing the role of these two diametrically opposing hormones on the glucose level not just in obesity but in different glucose tolerance states by looking at the hormone levels and at the insulin glucagon bipolar axis itself." (PMID 38665134, 2024). "In the VAT of individuals with obesity and prediabetes, GLP-1 shifted its metabolic profile by increasing alanine and lactate production while also decreasing isoleucine consumption, whereas GIP and glucagon decreased lactate and alanine production and increased pyruvate consumption." (PMID 37233628, 2023). "As such, glucagon infusions were initially posited as a therapeutic anti‐obesity tool, although this is not practical due to significant health risks associated with glucagon‐mediated, enhanced release of fatty acids, hypoaminoacidaemia, uraemia, and muscle wasting." (PMID 36056607, 2022). "In our study, the level of glucagon was higher in patients with stable plaques without obesity, which could just indicate its protective properties." (PMID 36013196, 2022). "Our finding that glucagon administration does not affect reproductive hormones in healthy men provides important data on potential off-target effects in the ongoing development of glucagon receptor agonists for the treatment of obesity." (PMID 32232363, 2020). "However, novel dual receptor agonists have been developed for the treatment of obesity and T2D under the concept that GLP-1 restrains the hyperglycemic action of glucagon, while allowing it to exert its beneficial actions on bodyweight, food intake, lipid metabolism and thermogenesis." (PMID 30459715, 2018). "Thus, it appears plausible that glucagon acting via the release of AVP/copeptin from targets in the hypothalamus and posterior pituitary is involved in this regulation and copeptin response is attenuated in obesity." (PMID 26578365, 2016). "Peptides derived from the glucagon gene Gcg, for example, glucagon and glucagon‐like peptide 1 (GLP‐1), act as physiological regulators of fuel metabolism and are thus of major interest in the pathogenesis of diseases, such as type‐2 diabetes and obesity, and their therapeutic management." (PMID 26634904, 2015). "The role of glucagon in response to hemorrhage has not been investigated in a model of obesity." (PMID 25472607, 2014). "Furthermore, earlier research suggested that increasing glucagon in obese mice reduces appetite and slows weight gain, indicating that glucagon may help regulate energy balance and obesity, not just raise blood sugar." (PMID 40822953, 2025).
Obesity (continued). "A crossover trial involving 12 T2DM patients with obesity with different interventions including ARNIs alone or ARNIs plus DPP4 inhibitors showed that ARNIs increase postprandial blood glucose by 57% with increasing levels of glucagon, C‐peptide, and GLP‐1 without effect on GIP and insulin levels." (PMID 37078106, 2023). "Although we find a weak correlation between fasting glucagon and glucose levels in subjects with IFG, glucagon concentrations are not elevated in subjects with IFG, as is the case in subjects with IGT (IGT, IGT+IFG, T2D), compared to normoglycemic individuals with overweight or obesity." (PMID 39027470, 2024).
Insulin resistance (444 papers, 2006 to 2026). Increased resistance towards insulin, that is, diminished effectiveness of insulin in reducing blood glucose levels. "EKA occurs due to relative or absolute carbohydrate deficit and insulin resistance or deficiency, leading to increased glucagon-to-insulin ratio." (PMID 39801610, 2025). "One explanation is that MASLD is closely associated with insulin resistance and the resulting failure of insulin to lower circulating blood glucose masks any lowering effect of glucagon signalling deficiency on glucose levels." (PMID 38579751, 2024). "In type 2 diabetes (T2D), which is the most common form of the disease, insulin resistance, relative insulin deficiency, impaired incretin effect, upregulation of glucagon levels, and increased renal glucose reabsorption are key pathophysiological features." (PMID 39335474, 2024). "Most notably, the pathways associated with insulin resistance and the glucagon signaling pathway were downregulated in the HOPO group." (PMID 39519607, 2024). "Previously, insulin resistance was associated with an altered response of glucagon and the HPA axis to glucose variations." (PMID 36752854, 2023). "For glucagon, insulin resistance was associated with a shift in estimated IC50 of insulin and was similar to the fasting insulin for insulin-sensitive individuals with a GIR20–60min ≥ 10.8 mg/kg-LBM/min of 5.1 μU/mL." (PMID 36752854, 2023). "Whilst insulin resistance is a well‐known pathogenic mechanism, the role of glucagon resistance has been underappreciated." (PMID 37208943, 2023). "Excess thyroid hormone stimulates lipolysis and the secretion of glucagon, followed by deterioration of glucose metabolism, which can cause glucose intolerance and insulin resistance in T2DM." (PMID 36589820, 2022). "In the present study, the association of glucagon and the glucagon–alanine index with plasma glucose and insulin resistance (HOMA-IR) represented this compensation." (PMID 33275161, 2021). "The beneficial effects of AITC given at the dose of 5 mg on insulin resistance and on blood glucose levels seems to be partially associated with decrease in blood glucagon." (PMID 35050980, 2021). "Recently, insulin resistance in pancreatic α cells has been proposed to be associated with glucagon dysregulation." (PMID 31357734, 2019). "For smoking, the nicotine in tobacco can raise blood sugar levels by increasing the levels of norepinephrine, epinephrine, glucocorticoid, and growth hormone glucagon levels in the body and can also reduce insulin secretion, thus causing insulin resistance." (PMID 30911549, 2019). "According to previous data, the body promotes physiological adaptations to insulin resistance by also increasing the suppression of glucagon levels in response to glucose, underlying the role of alpha cells during the development of insulin resistance." (PMID 31546230, 2019). "These assumptions are in line with our results obtained in obese adolescents where fasting glucagon levels were positively associated with insulin resistance." (PMID 26942445, 2016). "Taken together, these data indicate that FMO3 expression, which is directly inhibited by insulin and induced by glucagon and corticosteroids, is increased in male mice with insulin deficiency/insulin resistance." (PMID 25849138, 2015). "Other possible explanations include that insulin resistance may stem from relative hepatic insulin deficiency accompanying peripheral hyperinsulinemia or diminishing glucagon secretion suppression." (PMID 39287794, 2025). "This suggests that elevated glucagon may indirectly increase CAD risk by worsening insulin resistance." (PMID 41458542, 2025). "Altered glucagon and insulin signaling contribute to T2D, and insulin resistance may also be associated with cognitive decline." (PMID 40271226, 2025).